IKZF2 (IKAROS family zinc finger 2)
Description:
Transcription factor, which stabilizes the noninflammatory phenotype of regulatory T cells (Tregs) (By similarity). May possibly act via STAT5-mediated signaling (By similarity). Binds IL2 promoter and represses its transcription, possibly by epigenetic silencing, inducing deacetylation of core histones in the IL2 promoter. In Tregs, required for FOXP3 recruitment to the IL2 promoter (By similarity). Required for outer hair cells maturation and, consequently, for hearing (By similarity).
Synonyms: HELIOS; ZNFN1A2; ANF1A2; ICHAD; IMDIA; ZNF1A2
Tractability: Small molecule: a structure with a bound ligand is known. PROTAC: UniProt records ubiquitination sites on it; ubiquitination databases record sites on it.
Target class: Transcription factor
Chemical probes: ALV2 (high quality), DKY709 (high quality)
Gene: Protein-coding gene on chromosome 2 (212,999,691 to 213,152,427, reverse strand). Ensembl gene ENSG00000030419.
Subcellular location: Nucleus
Subcellular location (Human Protein Atlas): Nuclear bodies; Nucleoplasm; Cytosol
Pathways (Reactome):
Chromatin organization: Interaction of NuRD complexes with transcription factors
Gene Ontology:
Molecular function: DNA-binding transcription factor activity; protein binding; RNA polymerase II cis-regulatory region sequence-specific DNA binding
Biological process: regulation of transcription by RNA polymerase II; regulation of DNA-templated transcription
Cellular component: nucleus; nucleoplasm
Genetic constraint (gnomAD): Loss-of-function variants: 15 observed, 46.2 expected, observed/expected ratio (o/e) 0.32, 90% interval 0.22 to 0.5. The upper end of that interval is the gene's LOEUF score, 0.5, which puts it in group 2 of 6, group 1 being the genes least tolerant of losing a copy. Missense variants: 551 observed, 674.24 expected, observed/expected ratio (o/e) 0.82, 90% interval 0.76 to 0.88. Synonymous variants: 225 observed, 226.94 expected, observed/expected ratio (o/e) 0.99, 90% interval 0.89 to 1.11.
Homologues: Orthologues: chimpanzee IKZF2 (99% identical), macaque IKZF2 (99% identical), dog IKZF2 (99% identical), pig IKZF2 (99% identical), rabbit IKZF2 (99% identical), guinea pig IKZF2 (98% identical), mouse Ikzf2 (98% identical), rat Ikzf2 (97% identical), tropical clawed frog ikzf2 (79% identical), zebrafish ikzf2 (52% identical), Drosophila melanogaster CG14442 (7% identical), Drosophila melanogaster CG14440 (4% identical). Paralogues in human: IKZF4 (53% identical), IKZF1 (50% identical), IKZF3 (44% identical), ZNF567 (16% identical), ZNF382 (15% identical), ZNF613 (14% identical), ZNF350 (14% identical), ZNF649 (14% identical), ZNF639 (13% identical), ZNF821 (12% identical), ZNF564 (11% identical).
Diseases named in the same sentence as IKZF2 in open-access papers:
IKZF2 is named in the same sentence as 54 diseases in open-access papers, as found by Europe PMC text mining. Sharing a sentence is not in itself a finding about the gene and the disease. The quoted sentences say what the papers report.
leukemia (15 papers, 2015 to 2025). A malignant (clonal) hematologic disorder, involving hematopoietic stem cells and characterized by the presence of primitive or atypical myeloid or lymphoid cells in the bone marrow and the blood. "CCND2, DNMT3B, SOX4, and IKZF2, all previously reported to associate with leukemia development, were found within the positively correlated genes." (PMID 33597968, 2020). "In sharp contrast, stem cell gene, Cd34; lineage gene, Gata2; and leukemia stem cell regulator, Ikzf2; as well as Tnfaip3, Pvr (Cd155), and Nectin2 (Cd112), were upregulated in Vav-cre Tet2fl/flTp53fl/fl GMPs." (PMID 40111422, 2025). "This is partly due to their association with inborn errors of the immune system, thrombocytopenia, and/or predisposition to leukaemia (IKZF1 and IKZF3) and to somatic defects that are frequently occurring in haematological malignancies (IKZF1 and IKZF2)." (PMID 39406892, 2024). "The rs77756144 lies in-between the gene IKZF2 and SPAG16, among which the IKZF2 appears to be a probable candidate targeted for selection given its involvement in HTLV-1 infection related leukemia." (PMID 37903429, 2023). "IKZF2 is recently found to drive leukemia stem cell renewal and inhibit myeloid differentiation, by regulating HOXA9 and CEBP." (PMID 32571260, 2020). "Many of the predicted transcription factors have a known role in hematopoiesis and leukemia development (Ikzf2, Pbx3, and Hoxa13 for upregulated genes and Fos, Nkx2-2, Gata2 for downregulated genes)." (PMID 31186416, 2019). "Our lab previously found that MSI2 directly binds to the mRNA of mixed-lineage leukaemia target genes including Hoxa9, Myc and Ikzf2, and regulates the translation of these targets in a mixed-lineage leukaemia-AF9 leukaemia model." (PMID 26898884, 2016). "IKZF2 has been shown to drive leukemia stem cell self-renewal and inhibits myeloid differentiation." (PMID 36284352, 2022). "In addition to Myc and Bcl2, other tumor-promoting genes such as Eef2 and Myh10 were upregulated in leukemia cells, whereas tumor suppressors such as Ikzf1, Ikzf2, Arid1b, Arid2, Samhd1, Bach2, and Myo18b were downregulated." (PMID 34907175, 2021). "CDK6 was also found to be positively associated with genes identified to contribute to the development of leukemia, including CCND2, DNMT3B, SOX4, and IKZF2, as well as being negatively associated with anticancer microRNAs, including miR-187, miR-9, miR-582, miR708, and miR-362." (PMID 33597968, 2020). "However, Ikzf2, which builds the chromatin accessibility essential for leukemia stem cells, is dispensable for HSC maintenance." (PMID 32694618, 2020). "Moreover, we found that the enhanced RNA binding activity of MSI2 leads to differential regulation, e.g., at Hoxa9, Ikzf2, and Myb targets, in LSCs versus LSKs, which provides a possible explanation for the differential requirement of MSI2 in leukemia compared with normal hematopoiesis." (PMID 32332729, 2020).
systemic lupus erythematosus (10 papers, 2021 to 2025). An autoimmune multi-organ disease typically associated with vasculopathy and autoantibody production. "Cascade testing of the same kindred revealed that the five remaining siblings were also heterozygous for the IKZF2 variant, one of whom had lupus." (PMID 40465409, 2025). "At least one previous case has been reported of a heterozygous loss of function variant in IKZF2 presenting with lupus and incomplete penetrance." (PMID 40465409, 2025). "Very recently, a lupus-like phenotype was diagnosed in a patient with a germline mutation in the IKZF2 gene." (PMID 38203623, 2023). "Moreover, Helios downregulation was observed in some subsets of “memory-like” NK cells from cytomegalovirus-infected individuals, and finally, the proportion of CD16+ CD56dim NK cells was reduced in a lupus patient due to germline mutation of the IKZF2 gene." (PMID 38203623, 2023). "IKZF2 was identified as a lupus susceptibility locus, while its exact molecular function in LN is unknown." (PMID 35688845, 2022). "Three members, IKZF1 (IKAROS) (rs2366293-C, rs4917014-T), IKZF3 (AIOLOS) (rs2941509-T), and IKZF2 (HELIOS) (rs6435760-C) have been implicated in systemic lupus erythematosus (SLE)." (PMID 38885295, 2024). "In this review, we will discuss the possibility of considering the Helios transcription factor (encoded by the IKZF2 gene) as a potential biomarker and therapeutic target in systemic lupus erythematosus (SLE), a relatively common autoimmune disease." (PMID 38203623, 2023). "We identified two transcription factors (STAT1 and LTF) that were positively correlated with T-cell subset infiltration in the lupus tubulointerstitium, and three transcription factors (IRF8, RORC and IKZF2) that were positively associated with T-cell subset infiltration in the glomeruli." (PMID 36829595, 2023). "Furthermore, IKZF3 (Aiolos) and IKZF2 (Helios), and BACH2 have been implicated in other autoimmune diseases such as systemic lupus erythematosus (SLE) and Rheumatoid Arthritis (RA)." (PMID 36284352, 2022). "Notably, loss-of-function (LOF) variants in IKZF2 (HELIOS) were recently associated with combined immunodeficiency (CID) and/or immune dysregulation, including immune thrombocytopenia (ITP), Evan’s syndrome, and systemic lupus erythematosus." (PMID 40295428, 2025). "IKZF3 (Aiolos) and IKZF2 (Helios), and BACH2 have been implicated in other autoimmune disease such as systemic lupus erythematosus (SLE) and Rheumatoid Arthritis (RA)." (PMID 36284352, 2022). "Only older Ikzf2−/− mice at the age of 6–8 months spontaneously developed an autoimmune phenotype resembling some features of systemic lupus erythematosus (SLE) with infiltration of lymphocytes to non‐lymphoid organs, production of autoantibodies, and glomerulonephritis." (PMID 39354708, 2025).
Immunodeficiency (9 papers, 2021 to 2025). Failure of the immune system to protect the body adequately from infection, due to the absence or insufficiency of some component process or substance. "The initial descriptions were of germline heterozygous or homozygous LOF IKZF2 variants in a total of 13 patients with combined immunodeficiency and/or immune dysregulation." (PMID 40295428, 2025). "Recently, IKZF2 variants have been linked to combined immunodeficiency with immune dysregulation, with only 13 cases reported to date, most harboring heterozygous variants." (PMID 41394846, 2025). "Germline monoallelic and biallelic LOF variants in the IKZF2 gene, which encodes HELIOS, cause IEIs predominantly presenting with autoimmunity and immunodeficiency." (PMID 38773004, 2024). "A heterozygous loss-of-function variant in IKZF2 has been described in a single family, leading to immunodeficiency with increased immune activation and a profound reduction in mucosal-associated invariant T (MAIT) cells." (PMID 38187391, 2023). "Patients carrying the IKZF2 variant presented with a combined immunodeficiency phenotype characterized by recurrent upper respiratory infections, thrush, mucosal ulcers, and chronic lymphadenopathy." (PMID 38187391, 2023). "IKZF2 is highly expressed in CD8 T cells; consequently, individuals with IKZF2 pathogenic variants feature impaired T cell homeostasis and can present with an immunedysregulatory/autoimmune phenotype or a combined immunodeficiency phenotype." (PMID 36359748, 2022).
myeloid leukemia (4 papers, 2022 to 2024). A clonal proliferation of myeloid cells and their precursors in the bone marrow, peripheral blood, and spleen. "In myeloid leukemia, hnRNP Q upregulates mRNA targets, including the critical genes Myc, Hoxa9, and Ikzf2, and promotes the stem cell program." (PMID 38976670, 2024). "Regulation of the AML LSC program by IKZF2 thus provides a rationale to therapeutically target IKZF2 in myeloid leukemia." (PMID 36284352, 2022). "IKZF2 is highly expressed in stem cells from myeloid leukemia and is required for leukemogenesis by blocking their differentiation." (PMID 35847946, 2022).
adult T-cell leukemia/lymphoma (3 papers, 2020 to 2023). A peripheral (mature) T-cell neoplasm linked to the human T-cell leukemia virus type 1 (HTLV-1), adult T-cell leukemia/lymphoma is endemic in several regions of the world, in particular Japan, the Caribbean, and parts of Central Africa. "For istance, at chromosome 2q34, chromothripsis caused loss of the transcription factor IKZF2 which frequently undergoes intragenic deletions in adult T-cell leukemia/lymphoma (ATL), and that we also found deleted in ∼3% of our cth− T-ALL cases." (PMID 35974102, 2022). "The aberrant variation of IKZF2 was also reported in ovarian cancer cell lines, adult T cell leukemia and gastric cancer, suggesting IKZF2 as a potential oncogenes." (PMID 32571260, 2020). "IKZF2 belongs to the Ikaros transcription factor family and played a critical role in lymphocyte development and the genetic region spanning IKZF2 is frequently deleted in the HTLV-1 associated adult T cell leukemia/lymphoma (ATL)." (PMID 37903429, 2023).
asthma (3 papers, 2022 to 2024). "The locus 17q12-21 encodes several genes including ORMDL3, GSDMB, ZBPB2, and IKZF2, which in fact were linked to asthma in subsequent GWAS and eQTL analyses, and it is one of the most replicated asthma loci to date." (PMID 35055381, 2022).
autoimmune disease (3 papers, 2020 to 2025). A disorder resulting from loss of function or tissue destruction of an organ or multiple organs, arising from humoral or cellular immune responses of the individual to their own tissue constituents. "Nevertheless, both Ikzf2−/− and Treg-specific Ikzf2−/− mice develop progressive autoimmune disease associated with activated CD4+/CD8+ T cells, increased T follicular helper (TFH) and germinal center (GC) B cell numbers, autoantibody production, and increased proinflammatory cytokine production." (PMID 40295428, 2025).
Autoimmunity (3 papers, 2024 to 2025). The occurrence of an immune reaction against the organism's own cells or tissues. "Indeed, Ikzf2 knockdown with the Foxp3 promoter in mice is sufficient to induce autoimmunity." (PMID 39354708, 2025).
ovarian carcinoma (3 papers, 2020 to 2021). A malignant neoplasm originating from the surface ovarian epithelium. "Decreased cell viability with this HDAC6 targeting PROTAC was previously shown to result from targeted degradation of IKAROS family zinc finger (IKZF) proteins at micromolar doses, although we did not measure any significant expression of IKZF1 and IKZF2 in ovarian cancers." (PMID 33322608, 2020).
rheumatoid arthritis (3 papers, 2017 to 2022). A chronic, systemic autoimmune disorder characterized by inflammation in the synovial membranes and articular surfaces. "In vitro experiments, it was found that IKZF2 deficient mice would acquire an auto-inflammatory phenotype similar to rheumatoid arthritis." (PMID 35688845, 2022). "IKZF2 deficient mice acquire an auto-inflammatory phenotype in later life similar to rheumatoid arthritis, with increased numbers of activated CD4+ and CD8+ T-cells, T-follicular helper cells, and germinal centre B-cells, which culminates in autoantibody production." (PMID 29059182, 2017).
acute myeloid leukemia (2 papers, 2020 to 2021). Acute myeloid leukemia (AML) is a group of neoplasms arising from precursor cells committed to the myeloid cell-line differentiation. "For example, in acute myeloid leukemia (AML), MSI2 expression has been shown to be an adverse prognostic marker that maintains the self-renewal program in AML by interacting with HOXA9, MYC, and IKZF2 mRNAs." (PMID 32448269, 2020).
B-cell lymphoma (2 papers, 2022 to 2024). "Consistent with previous studies, in B-cell lymphoma, MSI2 binds to canonical targets such as MYB and IKZF2, and Ro treatment resulted in their loss of protein abundance." (PMID 36167829, 2022). "Additionally, noteworthy genes, including IKZF2, CCL4, SAA1, and CD40, exhibited differential expression in the TCL group compared to the B-cell lymphoma (BCL) group." (PMID 39911484, 2024).
breast carcinoma (2 papers, 2025). "Meanwhile, compared with normal breast epithelium cells, the expression levels of IKZF2, NAB1, S100B were significantly downregulated in breast cancer cells." (PMID 40520263, 2025). "Compared with normal breast epithelium cells, RFX5, VEGFA were upregulated in breast cancer cells, IKZF2, NAB1, S100B were downregulated in breast cancer cells while F2R, S1PR2 showed no significance." (PMID 40520263, 2025).
coronary heart disease (2 papers, 2015 to 2022). "The IKZF2 rs12619285 polymorphism is associated with the eosinophil count, which has multidimensional functions in the pathogenesis of coronary heart disease (CHD)." (PMID 25780427, 2015).
glioblastoma (2 papers, 2024). The most malignant astrocytic tumor (WHO grade IV). "Whole-genome CRISPR/Cas9 screening was performed in CAR-T cells and co-cultured with Glioblastoma (GBM) stem cells (GSCs) to explore the PD-1 dependence genes such as TLE4 and IKZF2 for cancer treatment." (PMID 38816739, 2024).
ICHAD syndrome (2 papers, 2024 to 2025). "In our original description of ICHAD syndrome, we established that mRNA for the exon 5-duplicated IKZF2 variant is expressed in patient primary cells." (PMID 40295428, 2025). "Our group recently expanded this list through the discovery of 2 patients with germline DN IKZF2 variants who presented with ICHAD syndrome." (PMID 40295428, 2025). "During the present study of IKZF2, HL was also associated with IKZF2 since monoallelic variants affecting ZFs 3 and/or 2, were described in ICHAD syndrome (Immunodysregulation, Craniofacial anomalies, Hearing impairment, Athelia and Developmental delay)." (PMID 39406892, 2024).
Achalasia (1 paper, 2016). A disorder of esophageal motility characterized by the inability of the lower esophageal sphincter to relax during swallowing and by inadequate or lacking peristalsis in the lower half of the body of the esophagus. "Interestingly, in our results, IRF4 and BLIMP1 are important upstream regulators of genes down-regulated, such as XBP1, IGHM, CD79A, RORC, and IKZF2, stressing the implications of the immune-inflammation network in achalasia." (PMID 27511445, 2016).
adrenal autoimmunity (1 paper, 2025). "Beyond common variants, rare variants in immune genes such as RAG1, TNFAIP3 (A20), LAT, and IKZF2 (HELIOS) have been described in autoimmune syndromes that include adrenal autoimmunity." (PMID 41465179, 2025).
Allergy (1 paper, 2023). An allergy is an immune response or reaction to substances that are usually not harmful. "Compared with steady state, both tolerance and allergy conditions suppressed Ctla4 and upregulated Ikzf2." (PMID 37191720, 2023).
ANCA associated vasculitis (1 paper, 2022). "In addition, we valued IKZF2 expression in IgA Nephropathy and ANCA associated vasculitis, verifying our conclusion in a broader range." (PMID 35688845, 2022).
colitis (1 paper, 2022). Inflammation of the colon. "Some investigators have characterized cells with high levels of Ikzf2 and low expression of IL7 receptors as terminal effector CD8 + T cells, which fits a profile of the T-Ikzf2 identified in colons of mice developing colitis." (PMID 36058945, 2022).
Ewing sarcoma (1 paper, 2025). A small round cell tumor that lacks morphologic, immunohistochemical, and electron microscopic evidence of neuroectodermal differentiation. "Data 5), we selected six MTFs (TCF12, SOX6, POU3F1, POU3F2, NKX2-2, and IKZF2) as putative members of the Ewing sarcoma CRC, based on fulfilling at least two out of these three criteria." (PMID 41444391, 2025). "The three MTFs (POU3F2 & SOX6 & IKZF2) colocalised in 50% of top 100 Ewing sarcoma SEs." (PMID 41444391, 2025).
gastric tumor (1 paper, 2020). "Here, we examined the expression of a specific zinc finger transcription factor, Helios (IKZF2), in gastric tumor-infiltrating lymphocytes by immunohistochemistry and the correlation with survival." (PMID 32927747, 2020).
glaucoma (1 paper, 2018). Increased pressure in the eyeball due to obstruction of the outflow of aqueous humor. "We also investigated 9 novel glaucoma-associated loci from UKB in GERA, and 6 of the novel loci replicated at Bonferroni significance (near IKZF2, CADM2, near DGKG, ANKH, EXOC2, and LMX1B)." (PMID 29891935, 2018).
lymphoma (1 paper, 2023). A malignant (clonal) proliferation of B- lymphocytes or T- lymphocytes which involves the lymph nodes, bone marrow and/or extranodal sites. "These include the lymphoma related BCL11A gene, the IKZF2 gene involved in lymphocyte development or the transcription initiator GTF2H1." (PMID 36961799, 2023).